DPP4 (dipeptidyl peptidase 4)
Diseases named in the same sentence as DPP4 in open-access papers (continued):
Sharing a sentence is not in itself a finding about the gene and the disease.
COVID-19 (continued). "In T2DM, which is an established risk factor for COVID-19 disease course, the circulating DPP4 activity was found to be significantly increased in prior reports." (PMID 35195023, 2022). "Serum DPP4 activity is associated with COVID-19 severity and is a strong prognostic biomarker of mortality." (PMID 35195023, 2022). "Different mechanisms have been proposed to be associated with the effect of DPP-4 inhibitors in patients with COVID-19." (PMID 35017617, 2022). "So far, we found that DPP-4 inhibitor treatment is associated with increased sFRP5 serum concentrations and that COVID-19 is related to sFRP5 deficiency." (PMID 36056109, 2022). "The studies indicated DPP4 dysregulation and late inflammatory immune response caused by lung injury among COVID-19 patients." (PMID 34696302, 2021). "In one study, incorporating 8 retrospective and prospective cohort studies and 1 case series, concluded that use of DPP-4 inhibitors was associated with 24% lower mortality in patients with COVID-19 (risk ratio 0.76, 95%-CI 0.60–0.97)." (PMID 34222054, 2021). "Inhibitors of DPP4 conferred a 7-fold lower risk of COVID-19 mortality among patients with metabolic diseases." (PMID 34335974, 2021). "Since metabolic diseases are major risk factors for the present COVID-19 pandemic, we examined circulating soluble DPP-4 serum concentrations in patients suffering from severe COVID-19 infection and in healthy human subjects in a case control design." (PMID 32958905, 2020). "A case series involving 387 COVID-19 patients in Italy described the association between DPP4 inhibitors treatment and a statistically reduced mortality, but the result was based on only 11 patients." (PMID 33584268, 2020). "In conclusion, our analysis of nationwide Korean data suggests that DPP-4 inhibitor use in diabetic patients hospitalized with COVID-19 may be associated with reduced disease severity and mortality." (PMID 40869643, 2025). "This dual effect, limiting viral entry and modulating immune responses, may underlie the observed mortality benefit, with DPP-4 inhibitors also possibly alleviating hypertension-related comorbidities in COVID-19." (PMID 40869643, 2025). "However, some contradictory results have been also reported since administration of DPP-4 inhibitors and sulfonylureas was associated with adverse outcomes and mortality in COVID-19 patients." (PMID 38378550, 2024). "Our findings on DPP-4 inhibitors are limited to only a few studies, future research needs to be done to determine underlying mechanisms contributing to patient outcomes in individuals diagnosed with DM and COVID-19." (PMID 39835258, 2024). "The SARS-CoV-2 virus, which causes COVID-19, can bind to DPP4 to enter and infect cells." (PMID 37896834, 2023). "Moreover, a significant decrease in serum DPP4 activity was found in COVID-19 inpatients, which was associated with severe COVID-19 disease and mortality." (PMID 36009573, 2022). "A recent study showed that mutations in DPP4 were more evident in COVID-19 asymptomatic patients." (PMID 36553622, 2022). "When the authors defined a covariate as having a confounder effect provided that the change in p-value (for association between DPP4 activity and mortality in COVID-19) was at least 1 log, then only the plasma glucose and serum albumin concentrations were identified as confounding factors." (PMID 35195023, 2022). "In addition, a variant promoter region of the DPP4 gene inherited from Neandertals was reported to double the risk of becoming critical ill with COVID-19." (PMID 35195023, 2022). "However, it has been observed that the usage of DPP-4 inhibitors was linked to decreased mortality in COVID-19 patients." (PMID 35822018, 2021). "DPP-4 inhibitors are predicted to exert a protective effect on the progression of coronavirus disease 2019 (COVID-19)." (PMID 34015003, 2021).
COVID-19 (continued). "Acute respiratory distress syndrome (ARDS) is the leading cause of death in COVID-19 patients, and DPP4 inhibitors may be a new treatment approach because they can decrease the production of inflammatory factors such as IL-1β, TNF-α, and IL-6." (PMID 34955820, 2021). "Moreover, high circulating Ang II in patients with COVID-19 activates renal expression of DPP4 which is causing glomerular and tubular injury." (PMID 34629845, 2021). "Most recent study also unraveled that another Neanderthal variants at chromosome 2q24.2 on the proximal promoter region of DPP4 can double or quadruple the risk of becoming critically ill with COVID-19, such as hospitalization and requiring mechanical ventilation." (PMID 34335974, 2021). "It was also hypothesized that dipeptidyl peptidase 4 (DPP4) could be a functional receptor for the S protein of SARS-CoV-2; if so, the DPP4 inhibitors may play a role in preventing and decreasing the risk and progression of COVID-19." (PMID 34451827, 2021). "Similar to ACE2, conditions with DPP4 upregulation are associated with severe COVID-19." (PMID 32838195, 2020). "In an experimental model of ARDS, which is associated with high severity and mortality among COVID-19 patients, the DPP4 inhibitor sitagliptin decreased histological signs of lung injury by hindering the release of pro-inflammatory cytokines IL-1β, TNFα, and IL-6." (PMID 32719619, 2020). "Therefore, future prospective cohort studies and randomized controlled trials are warranted to confirm the protective association of DPP-4 inhibitors observed in our analysis and to further elucidate their potential role in improving outcomes among diabetic patients with COVID-19." (PMID 40869643, 2025). "Therefore, DPP4 inhibitors may be of potential use for halting progression to the hyperinflammatory and pro-fibrotic state associated with severe COVID-19." (PMID 36009573, 2022). "The temporal relationship between drug administration, viral infection, and onset of autoimmune disease indicates a possible interaction between COVID-19-induced immune dysregulation and DPP-4 inhibition." (PMID 40895902, 2025). "FXR/RXR, DPP4, JAK2, and ACE are associated with COVID-19, while CNGA1, BLT1, COX2, and 5-LOX are linked to pharyngitis." (PMID 40076279, 2025). "This case adds to a small but growing body of evidence suggesting that clinicians should be vigilant for BP in older diabetic patients with COVID-19 receiving DPP-4 inhibitors." (PMID 40895902, 2025). "Potential pharmacological interactions between DPP-4 inhibitors and medications commonly used in hospitalized COVID-19 patients warrant consideration." (PMID 40869643, 2025). "Our study is the first to examine the impact of DPP-4 inhibitors on COVID-19 mortality rates using nationwide big data from South Korea." (PMID 40869643, 2025). "Through additional subgroup analyses by insulin and ARB use, we aimed to refine our understanding of the potential mortality-reducing effects of DPP-4 inhibitors in diabetic patients with COVID-19." (PMID 40869643, 2025). "Taken together, these findings reinforce the potential therapeutic role of DPP-4 inhibitors in mitigating COVID-19 severity through both glycemic and pleiotropic mechanisms, warranting further mechanistic and prospective interventional studies." (PMID 40869643, 2025). "We compared the proteins of age-matched COVID-19 plasma samples and detected 13 elevated proteins, including DPP4, that were common between the SASP and the plasma of patients with severe COVID-19 compared to the control COVID-19 plasma samples." (PMID 37728586, 2024). "We found that 13 SASP-related proteins, including DPP4, were increased in the cohort of elderly and severely ill COVID-19 patients." (PMID 37728586, 2024). "A recent study has shown that ACE2 and dipeptidyl peptidase 4 (DPP4) enzymes were found to be genomic biomarkers elevated in naso-oropharyngeal swabs of COVID-19 patients." (PMID 38398672, 2024).
COVID-19 (continued). "Regarding the synergistic side effects between the COVID-19 vaccine and medications, there have been reports highlighting the potential for the onset of bullous pemphigoid when taking dipeptidyl peptidase 4 inhibitors (DPP4-i) after COVID-19 vaccination." (PMID 38883010, 2024). "Our data show that DPP4 is significantly elevated in severely ill patients with COVID-19 in an age-matched comparison." (PMID 37728586, 2024). "To investigate the effects of COVID-19 infection on DPP4 levels, we used plasma samples from a cohort of patients with COVID-19." (PMID 37728586, 2024). "Our results will aid the rational optimization of DPP4 as a potential therapeutic target to manage COVID-19 disease severity." (PMID 37896834, 2023). "A recent clinical study showed that COVID-19 patients had reduced levels of soluble DPP-4 (sDPP-4), possibly due to reduced shedding of the catalytic domain from its transmembrane domain compared with the uninfected healthy subjects." (PMID 37064327, 2023). "Preliminary reports on the beneficial effects of DPP-4 inhibitors on COVID-19 are, so far, promising." (PMID 37064327, 2023). "Clinical trials have started to validate the findings reported from the different parts of the globe claiming anti-DPP-4 drugs as therapeutics against COVID-19." (PMID 37064327, 2023). "A dipeptidyl peptidase-4 (DPP-4) inhibitor is a potential candidate for downregulating the hyperinflammation in COVID-19 patients." (PMID 36776226, 2023). "A recent study conducted on a total of 338 COVID-19 inpatients revealed that the administration of sitagliptin, a DPP-4 inhibitor, upon admission yielded substantial benefits." (PMID 37626788, 2023). "Based on the existing observational studies, it remains challenging to arrive at definitive conclusions regarding the impact of pre-existing DPP-4 inhibitor (DPP-4is) therapy on COVID-19 outcomes." (PMID 37626788, 2023). "More randomized and real-world trials are necessary to reach any conclusion regarding the role of DPP-4 inhibitors in regulating COVID-19." (PMID 37064327, 2023). "Dipeptidyl peptidase-4 inhibitors are another group of antidiabetic drugs recognized for managing and controlling the effects of COVID-19 among diabetic patients." (PMID 37893528, 2023). "Several clinical trials are currently underway to evaluate the safety and efficacy of DPP4 inhibitors in patients with COVID-19." (PMID 37896834, 2023). "It was evidenced that treatment with sitagliptin, the inhibitor of CD26 enzymatic activity as dipeptidyl peptidase-4, reduced mortality in patients hospitalized for COVID-19." (PMID 37685949, 2023). "Several studies also reported that targeting DPP4 has been considered a pharmacologically important strategy in patients suffering from severe respiratory diseases related to coronaviruses and COVID-19." (PMID 36839456, 2023). "There are much less data on the impact of DPP-4 inhibitors on the outcomes of COVID-19, and the available information is contradictory." (PMID 36017317, 2022). "The beneficial effect of DPP4 inhibitors on COVID-19 outcomes was raised; however, only retrospective analyses are available and not all of these reports consistently demonstrated a beneficial effect; the results from prospective trials are lacking." (PMID 35195023, 2022). "In this sense, the structure and the physiological activities of DPP4 will be outlined, focusing on endogenous glycemic control and the immune system, due to their implications on COVID-19 progression." (PMID 36009573, 2022). "The dipeptidyl peptidase-4 inhibitor is considered a potential therapy for COVID-19 and has similarly shown organ protection in DKD." (PMID 36341356, 2022). "Serum DPP4 activity was assessed in a total of 184 individuals, including 102 hospitalized patients with COVID-19, 43 post-COVID-19 plasma donors and 39 individuals who were never exposed to SARS-CoV-2 (with sampling prior to the pandemic)." (PMID 35195023, 2022).
COVID-19 (continued). "In addition, the inverse correlation between DPP4 activity and D-dimer levels also urges further experimental research in particular, due to the fact that the increased D-dimer levels and thromboembolic events observed during the COVID-19 disease course and are associated with short-term mortality." (PMID 35195023, 2022). "Serum DPP4 activity as a biomarker is characterized with competitive test attributes among the recently proposed tests in COVID-19, in particular with the currently reported performance measures, including ROC curves." (PMID 35195023, 2022). "Clinical literature on DPP4 inhibitors in COVID-19 is ambiguous; several studies and meta-analyses have showed favorable effects, while some have not." (PMID 36145576, 2022). "Altogether, these observations indicate that DPP4 is an important regulator of the immune system and therefore can contribute to the comorbidities of COVID-19." (PMID 36009573, 2022). "We previously reported decreased concentrations of DPP4 in individuals with hypoalphalipoproteinemia and those with COVID-19 that required mechanical ventilation." (PMID 35885620, 2022). "While DPP4 inhibitors have been tested as a treatment for COVID-19, the results are still inconclusive." (PMID 35655307, 2022). "In order to highlight the importance of DPP4 in COVID-19, two monoclonal antibodies targeting this protease have been designed to treat COVID-19 patients." (PMID 36009573, 2022). "Overall, our network analysis indicates that DPP4 inhibitors are related to a better prognosis for COVID-19 and thus represent potential repositioning drugs against SARS-CoV-2." (PMID 36145576, 2022). "We next carried out further correlation with the three biomarkers, DPP4 (the most differentially regulated protein in the post-COVID-19 BAL), LDH, and albumin, as markers of ongoing damage in the airways." (PMID 35151371, 2022). "Berbamine, isolated from Berberis amurensis Rupr., demonstrated its anti-COVID-19 activity by causing a reduction in ACE2 and dipeptidyl peptidase-4 (DPP-IV) levels in the plasma membrane." (PMID 36671402, 2022). "In a recent meta-analysis addressing the potential impact of DPP4 inhibitors on COVID-19-related death, it was demonstrated that when they were administered in the inpatient setting, DPP4 inhibitors decreased the risk for COVID-19-related death by 50%." (PMID 36009573, 2022). "Consistently, a few authors suggested, based on these theoretical points regarding DPP4 activity in at-risk medical conditions, that the increased circulating levels of soluble DPP4 should contribute to the severity of COVID-19." (PMID 35195023, 2022). "This review aims to update the field of DPP4 and COVID-19, trying to unravel the putative mechanisms by which the protease plays a role in the course of the infection by SARS-CoV-2." (PMID 36009573, 2022). "Inhibition of DPP-4 activity to reduce the severity of COVID-19 has been under investigation, but there are little data to support its use at present, either prophylactically or during infection." (PMID 35318939, 2022). "It is remarkable that serum DPP4 levels and activity were significantly lower in COVID-19 patients at hospital admission compared to healthy controls." (PMID 36009573, 2022). "The human DPP4-encoding gene, located on chromosome 2q24.2 with 28 exons, contains almost 35,000 polymorphic sites, a few of which are associated with clinical conditions such as T2DM, myocardial infarction, dyslipidemia and coronavirus disease 2019 (COVID-19) (14, 19–, 21)." (PMID 36197412, 2022). "DPP-4 inhibitors are currently investigated as a therapeutic approach preventing cardiovascular complications in COVID-19 due to their anti-inflammatory effects at the vascular level." (PMID 35331159, 2022). "A review of clinical trials with the DPP4 inhibitor sitagliptin found that most studies showed a favorable effect on COVID-19 progression." (PMID 36145576, 2022).
COVID-19 (continued). "Serum DPP4 activity significantly correlated with clinically meaningful parameters in COVID-19, including the patients' ages, absolute lymphocyte count and serum albumin, C-reactive protein, IL-6 and plasma D-dimer levels." (PMID 35195023, 2022). "This study points to DPP4 as a binding target for SARS-CoV-2 and reinforces DPP4 as a very promising target to attenuate COVID-19 severity." (PMID 33648564, 2021). "In this Perspective article we propose vitamin D and dipeptidyl peptidase-4 (DPP-4) inhibitors as potential candidates for prevention and modulation of cytokine storm in patients with COVID-19 based on the most recent evidence." (PMID 33906375, 2021). "In COVID-19, the dynamic of correlation between DPP4/CD26 localization and site of lung inflammation appeared to be confirmed." (PMID 34452531, 2021). "For this reason, DPP4Is reduce COVID-19 virulence through the suppression of DPP4/CD26-dependent inflammatory signaling with subsequent inhibition of CS and disease progression." (PMID 34124187, 2021). "DPP4 inhibitors (DPP4i) have been developed for diabetic glucose control and are being investigated for treatment of COVID-19 patients with pre-existing diabetic conditions (ClinicalTrails.gov identifier NCT04542213)." (PMID 33919584, 2021). "Of those, the oral dipeptidyl peptidase (DPP)-4 inhibitors are of high interest in patients with COVID-19 for several reasons." (PMID 34222054, 2021). "The possible role of DPP4 in the pathogenesis of severe and fatal COVID-19 conditions that occur in certain populations of individuals should further be considered." (PMID 33562193, 2021). "Although there is a lack of evidence for the combination of the S1 protein with DPP4, the roles of DPP4 and DPP4 inhibitors in COVID-19 have been increasingly realized." (PMID 34955820, 2021). "Both higher levels of ANPEP in monocytes and granulocytes and higher levels of DPP4 in T cells and dendritic cells were observed in COVID-19 patients compared with HC." (PMID 34349096, 2021). "With this available evidence, the anti-inflammatory properties of DPP-4 inhibitors suggest their potential implication in DN and COVID-19 immunopathogenesis, and DPP-4 represents a potential target to reduce the pathological progression of both diseases." (PMID 34360529, 2021). "DPP4 and its inhibitors have been shown to play pivotal roles in lung diseases, such as COVID-19 and pulmonary fibrosis." (PMID 34955820, 2021). "Although a recent molecular docking study did not support the effective interaction between DPP4 and SARS-CoV-2 spike protein for virus entry, blockade of ACE2 and DPP4 has been proposed as a preventive strategy for COVID-19." (PMID 34682694, 2021). "Lowered DPP-4 levels and restoration of AMPK levels are organ-protective, suggesting a pathogenic role of DPP-4 and a protective role of AMPK in diabetic COVID-19 patients." (PMID 34451848, 2021). "The anti-inflammatory effects of DPP-4 inhibitors have been projected to mitigate the excessive inflammation reported in severe and critically ill cases of COVID-19." (PMID 32718020, 2020). "Yet, the use of DPP-4 inhibitors in the treatment of COVID-19 patients requires extensive investigation." (PMID 32718020, 2020). "The prevalence of ACE2 and DPP4 expression in the differentiated intestinal cells representing enterocytes also suggests that GI infection is a common feature of COVID-19." (PMID 32969768, 2020). "We analyzed 131 COVID-19 patients by exome sequencing and examined the genetic variants of TMPRSS2, PCSK3, DPP4, and BSG genes." (PMID 32867305, 2020). "Currently, most data point towards membrane bound ACE2 in contrast to DPP-4 as the major binding partner for COVID-19 internalization into host immune cells." (PMID 32958905, 2020). "As another example relevant to drug repurposing and the ideal strategy for confronting COVID-19, the specific role of DPP4 on COVID-19 remains to be investigated." (PMID 32325767, 2020).